SLC7A5 (solute carrier family 7 member 5)
Diseases named in the same sentence as SLC7A5 in open-access papers (continued):
Sharing a sentence is not in itself a finding about the gene and the disease.
cancer (continued). "LAT1, also known as the solute carrier 7A5 (SLC7A5), is a light-chain heteromeric amino acid transporter of neutral essential amino acids, including methionine on the cancer cell membrane, and its suppression inhibits mTORC1 activation through limiting the intracellular level of amino acids." (PMID 40299656, 2025). "The L-Leu amino acid transporter SLC7A5 has become an important target in inflammation and cancer." (PMID 40399490, 2025). "SLC1A5, SLC3A2, and SLC7A5 are upregulated in various cancer types, which underpins the increased demand for bulk protein synthesis owing to the enhanced proliferation of cancer cells." (PMID 39757767, 2025). "MT2A and SLC7A5 may be oxaliplatin-resistant genes unique to GC and thus were not significantly correlated with drug sensitivity in the pan-cancer database." (PMID 40133832, 2025). "SLC1A5 functionally couples with SLC7A5 and promotes mTOR activation in cancer cells." (PMID 40362545, 2025). "Most cancer immune cycles were more active in patients with high SLC7A5." (PMID 38790003, 2024). "The promoter methylation of SLC7A5 showed an opposite trend to the gene expression in most cancers." (PMID 38790003, 2024). "Anti-SLC7A5 combined with cancer immunotherapy may have greater effectiveness than either therapy alone." (PMID 38790003, 2024). "Cancer cells express SLC7A5 primarily in their plasma membranes." (PMID 38790003, 2024). "Additionally, for a comprehensive assessment of the expression patterns and immunological roles of SLC7A5, pan-cancer analysis was performed using cancer genomics datasets." (PMID 38790003, 2024). "Interestingly, in several human cancers, SLC7A5 has also been observed to be overexpressed (Zhao, Wang & Pan, 2015)." (PMID 39161963, 2024). "In order to identify cancer types that may benefit from anti-SLC7A5 immunotherapy, a pan-cancer analysis describing SLC7A5’s immune role is essential." (PMID 38790003, 2024). "This may be because the impact of SLC7A5 on the tumor immune microenvironment is greater than its impact on the tumor itself, thus exerting an anti-cancer effect." (PMID 38790003, 2024). "The study found a positive correlation between SLC7A5 and immunomodulators in most cancers." (PMID 38790003, 2024). "Finally, Cluster 3 is characterized by up-regulation of SLC1A5 and SLC7A5 that promotes cancer cell dependence on glucose and increases the need of cytosolic NADPH sustained by concomitant up-regulation of G6PD." (PMID 36083313, 2023). "SLC7A5 has been reported to be expressed at abnormally high levels in esophageal cancer, hepatocellular cancer, breast cancer, colon cancer and other cancers, and it could be used as a prognostic factor." (PMID 36505791, 2022). "SLC7A5 is a candidate molecular target for cancer diagnosis and therapy." (PMID 36090994, 2022). "Moreover, the expression of the amino acid transporter SLC7A5 was significantly higher in hot tumors than in cold tumors, supporting a role for SLC7A5 in anti-tumor immunity in human cancers." (PMID 35103755, 2022). "SLC7A5-mediated import of leucine, as well as other essential AAs, is crucial for cancer cells." (PMID 35755805, 2022). "Also, this shows that treatment of cancers with a SLC7A5 inhibitor or a combination of SLC7A5 and SLC3A2 inhibitors would be more effective than treatment with SLC3A2 inhibitor alone." (PMID 33953707, 2021). "This study shows that in tumor tissues, increased levels of SLC7A5 may represent an adaptation mechanism for resistance to oxidative stress in cancer cells through regulating epigenetic modifications." (PMID 33401748, 2021). "This was Central Carbon metabolism in Cancer with three associated genes EGFR, NTRK3, and SLC7A5." (PMID 33317464, 2020).
cancer (continued). "Among the 14 SLC7 family genes, SLC7A5 has been most widely investigated in various cancers." (PMID 30558624, 2018). "In addition, miR-6775-3p also directly inhibits its host gene SLC7A5 which has been reported to play oncogenic roles in cancer progression." (PMID 30333480, 2018). "SLC7A5 is widely expressed in many human cancers and various cancer cell lines." (PMID 29566741, 2018). "SLC7A5 has been demonstrated to play an oncogenic role in cancer progression." (PMID 30333480, 2018). "SLC7A5 functions by importing essential amino acids to cancer cells and research has detailed the role of amino acids, particularly leucine, in activating mTORC1, which in turn controls protein translation and cell proliferation, and prevents apoptosis in malignant cells." (PMID 29566741, 2018). "For example, SLC1A5 takes up l-glutamine which is then exchanged for mTOR-activating l-leucine and other essential amino acids via the bidirectional antiporter SLC7A5, and both SLC1A5 and SLC7A5 are overexpressed in cancers along with glutamine transporter, SLC6A14." (PMID 28350329, 2017). "Inhibition of SLC7A5 protein expression reduced cancer cell proliferation in some types of cancer." (PMID 26244545, 2015). "In cancer, SLC7A5 dysregulation may disrupt DDR and lead to therapy resistance." (PMID 39994841, 2025). "Furthermore, we observed specific overexpression of SLC7A5 in TME of various cancers." (PMID 38790003, 2024). "Similarly, in other cancer cell lines, SLC7A5 plays an important role in leucine uptake." (PMID 38790003, 2024). "Therefore, SLC7A5 has been proposed as a novel target for the treatment of human cancers." (PMID 39161963, 2024). "As a result, SLC7A5 may be a molecular target in the diagnosis and treatment of cancer." (PMID 38790003, 2024). "Interestingly, the interaction weights between SCL7A5-positive cancer cells and other cells were significantly higher than that of SLC7A5-negative cancer cells, indicating that SLC7A5 might led a potential role in cell communication." (PMID 37731509, 2023). "In addition, we noticed that some ligand-receptor pairs, including integrin, ERK, Notch signaling pathways, might involve in communication between SLC7A5-positive cancer cells and other immune cells." (PMID 37731509, 2023). "Also, SLC7A5 overexpression blocked the anti-cancer effects of miR-138-5p in RB cells." (PMID 36619866, 2022). "In addition, SLC7A5 is upregulated in cancer cells and exhibits high cancer specificity." (PMID 36324584, 2022). "Moreover, SLC7A5 can promote cancer proliferation via AKT/mTORC1 pathway activation." (PMID 35986300, 2022). "Many cancer subtypes showed the overexpression of amino acid transporters SLCA14 (ATB0,+) and SLC7A5 (LAT-1)." (PMID 41451409, 2025). "Then, the top five higher binding energy ginsenosides were used for docking with other SLC transporters, including SLC7A5, SLC7A6, LCN2, and SLC7A9 cancer-related targets, as well as BSG due to its involvement in amino acid transport." (PMID 40566559, 2025). "Numerous studies documented that a variety of cancer cells overexpressed the methionine transporters (e.g., SLC43A2, SLC7A5, and SLC6A14) to uptake and outcompete methionine resource with immune cells." (PMID 41445748, 2025). "LAT1 (SLC7A5/SLC3A2) is broadly upregulated in rapidly proliferating tissues and many cancers, whereas LAT2 (SLC7A8/SLC3A2) exhibits wider expression in normal epithelia." (PMID 40507232, 2025). "The drug sensitivities of MT2A, SLC7A5, and NOTCH1 were predicted in this study using the pan-cancer database of oncoPredict." (PMID 40133832, 2025). "Various primary transporters, including B0AT1(SLC6A19), LAT1 (SLC7A5), SNAT5 (SLC38A5), and ASCT2 (SLC1A5), play significant roles in glutamine uptake by cancer cells." (PMID 40223274, 2025). "Thus, further studies may reveal the best SLC7A5 residue for targeting in cancer therapy." (PMID 38705513, 2024).
cancer (continued). "MiR-126 alters the biological functions of some genes such as PI3K, EGFL7, HOXA9, sKRAS, CRK, ADAM9, IRS-1, SOX-2, SLC7A5, and VEGF, as well as involves in inflammation, cell migration, angiogenesis, recurrence of cancer, and metastasis." (PMID 38445462, 2024). "Glutamine is transported into and out of cancer cells via specific transporters, such as SLC1A5 (ASCT2) and SLC7A5 (LAT1), which play integral roles in sustaining the increasing glutamine demands of proliferating cancer cells." (PMID 38473414, 2024). "In most cancers such as TGCT, LUAD, KIRP, ACC, and BRCA, the higher the tumor stage, the higher the SLC7A5 expression." (PMID 38790003, 2024). "SLC7A5, also known as the LAT1 receptor, is overexpressed in cancer cells compared to normal cells since cancer proliferation greatly depends on nutrients like essential amino acids." (PMID 39061185, 2024). "Specifically, in the functional coupling between SLC7A5 and SLC1A5, glutamine enters cancer cells through SLC1A5, which then effluxes out of the cells via SLC7A5, linked to the entry of leucine." (PMID 38459595, 2024). "In a pan-cancer analysis, SLC7A5 reflects several biological characteristics of TME, such as antitumor immunity, immunogenicity and cancer stemness, which is expected to be a predictor of ICB treatment response and tumor prognosis." (PMID 38790003, 2024). "Among the tumorigenesis-associated genes, KEGG analysis revealed that the upregulated genes, including SLC7A5, E2F1, HIF1A, VEGFA, and EGFR, were predominantly related to central carbon metabolism in cancer, the cell cycle, and the HIF-1 signaling pathway." (PMID 37328520, 2023). "Although various factors activate mTOR signaling, this study focused on two mTOR regulatory mechanisms: anti-cancer drug-induced mTOR signaling and L-type amino acid transporter 1 (LAT1) (also referred to as SLC7A5)-induced mTOR activation." (PMID 36768934, 2023). "Among the many amino acid transporters so far identified, SLC7A5 (LAT1) and SLC1A5 (ASCT2) are frequently overexpressed in cancer cells." (PMID 36599897, 2023). "Glutamine is transported into cancer cells by the glutamine transporter, such as SLC7A8 and SLC7A5, or synthesize de novo in cancer cells." (PMID 37127605, 2023). "In general, cancer cells exhibit enhanced glutaminolysis and glutamine uptake via membrane transporters like SLC1A5 and SLC7A5." (PMID 37887398, 2023). "L-type amino acid transporter 1 (LAT1, SLC7A5) is a Na+-independent neutral amino acid transporter highly expressed in various cancers to support their growth." (PMID 37626086, 2023). "One of the most upregulated AATs in cancer is the LAT1 system (L system, SLC7A5), which transports large neutral AAs, such as branched-chain and aromatic amino acids (leucine, tryptophan, phenylalanine or tyrosine, for example)." (PMID 35215275, 2022). "Consistent with these functions, the amino acid transporters SLC7A5 and SLC6A14 are upregulated in tumors, making then potential targets for the pharmacological treatment of cancer (Kanai, 2022; Nałęcz, 2020)." (PMID 35229720, 2022). "Preclinically, inhibitors of biosynthetic enzymes, such as the SBP enzyme PHGDH are under development for a wide array of cancers, and drugs to target amino acid transporters, such as LAT1 (SLC7A5), are also being explored." (PMID 36276057, 2022). "Cancer-upregulated l-type amino acid transporter 1 (LAT1; SLC7A5) supplies essential amino acids to cancer cells." (PMID 36357940, 2022). "Collectively, our data reveal that oncogenic KRAS alters the expression of AATs such as SLC1A5/ASCT2, SLC7A5/LAT1, and SLC38A2/SNAT2 and thereby increase the uptake of AAs to support cancer cell proliferation through mTOR activation." (PMID 34003553, 2021). "Amino acid transporters are upregulated in the different types of cancer, and many of them, such as CD98hc/SCL3A2, LAT1/SLC7A5, ASCT2/SLC1A5, emerged as promising molecular biomarkers, therapeutic targets, and novel tools for tumor imaging." (PMID 33401748, 2021).
cancer (continued). "In this study, we systematically analyzed the gene expression, epigenetic regulation, and genomic alterations of six key GLNM regulators (including SLC1A5, SLC7A5, SLC3A2, SLC7A11, GLS, and GLS2) across 33 different cancer types." (PMID 34573287, 2021). "In previous studies, the glutamine transporters SLC1A5, SLC7A5, SLC7A11, and SLC3A2 were found to be highly expressed in a variety of cancers." (PMID 34573287, 2021). "The Hippo pathway is seen to be downregulated in many cancer cells and when suppressed, the downstream proteins YAP1 and TAZ promote transcription of genes, like SLC7A5, that enhance cell proliferation." (PMID 33953707, 2021). "miR-126, contrary to miR-21 and miR-221, can act as a tumour suppressor in several carcinomas such as lung, gastric, breast and PDAC through the inhibition of epidermal growth-factor-like domain 7 (EGFL7), Crk, and SLC7A5." (PMID 33573274, 2021). "Most likely, these factors cooperate with MYC to maximize SLC7A5/SLC43A1 (and additional transporters) expression and EAA uptake in human cancers." (PMID 32651356, 2020). "JPH203 (also known as KYT-0353), a specific SLC7A5 inhibitor, can be evaluated as a MYC-selective cancer therapeutics in the future clinical trials." (PMID 32651356, 2020). "SLC7A5 functions in supplying amino acids to cancer cells as well as maintaining intra-cellular leucine, and SLC3A2 is required for the functional expression of SLC7A5 in tumour cells." (PMID 32093034, 2020). "Several previous studies have shown that SLC7A5 and SLC3A2 are prognostic markers in different types of cancer." (PMID 32093034, 2020). "In sum, CXCL3, SLC7A5, SLC26A2, GART, and CCDC68 genes were differentially expressed in three or more cancer types." (PMID 29843204, 2019). "Amino acid transporter LAT-1 (SLC7A5) and its chaperone CD98 also mediate uptake of neutral amino acids in cancer cells." (PMID 31333455, 2019). "SLC7A5 is co-expressed with the glutamine transporter, SLC1A5, in many cancers suggesting a functional coupling of these transporters in supporting tumour progression." (PMID 29566741, 2018). "In many cancer cells, amino acid transporters are upregulated to enable rapid cell growth and are therefore potential drug targets e.g. as SLC1A5, SLC6A15, SLC7A5, and SLC7A11." (PMID 29868606, 2018). "Relevant to cancer, the neutral amino acid transporters ASCT2/SLC1A5 and LAT1/SLC7A5 are known to have higher expression in certain tumors, and can mediate glutamine uptake in cell lines derived from these tumors." (PMID 28826492, 2017). "Taken together, these data revealed that an oxidative stress management network (SLC3A2, SLC7A5, and IGFBP3) under the control of p19-VHL performs an oncogenic role by overriding apoptosis in cancer stem cells." (PMID 28580172, 2017). "The L-type amino acid transporter-1 (LAT1, SLC7A5) is upregulated in a wide range of human cancers, positively correlated with the biological aggressiveness of tumors, and a promising target for both imaging and therapy." (PMID 24143237, 2013). "Contrary to the oncogenic role assigned by the literature, our analysis in Oncomine indicates that SLC7A5 and ID1 are negatively correlated with cancer progression." (PMID 20500816, 2010). "Thus, we considered that the strategy of SLC7A5 inhibition by L-Leu deprivation potentially fulfills the requirement of controlling GVHD onset and preventing cancer expansion." (PMID 40399490, 2025). "Simultaneously, the downregulation of WNT16, cell cycle regulators such as SLC7A5, and histone genes, like HIST2H3A and HIST1H2BJ, points to disruptions in the Wnt signaling and chromatin remodeling, processes central to cancer cell proliferation and epigenetic regulation." (PMID 40756515, 2025). "The L-Leu amino acid transporter SLC7A5 has become an important target in inflammation and cancer, but its role in aGVHD and GVT has not been explored before." (PMID 40399490, 2025).
cancer (continued). "Consequently, we selected five genes—INHBA, MMP7, PSAT1, SLC7A5, and TGFBI—to evaluate their mRNA expression levels in normal colon tissues compared to their corresponding cancer tissues." (PMID 39628390, 2024). "The unveiling of SLC1A5, SLC7A5, SLC6A14, and the SLC38 family transporters, along with their distinctive functional characteristics, enriches our comprehension of the intricate nature of glutamine transport in cancer." (PMID 38459595, 2024). "Additionally, previous studies reported that ESCC-associated proteins, including PCNA, SLC7A5, CTTN, RB1, EGFR, TP63, and PRMT1, exhibited increased expression in S-III; among these proteins, SLC7A5 and EGFR were FDA-approved drug targets for cancer treatment." (PMID 38652547, 2024). "Statistical analyses revealed a positive correlation between SLC7A5 overexpression and both overall survival and disease-free survival in early-stage but not late-stage cancers." (PMID 38722983, 2024). "L-type amino acid transporter 1 (LAT1; SLC7A5), which preferentially transports large neutral amino acids, including most of the essential amino acids, is known to be upregulated in various types of cancers." (PMID 37322479, 2023). "Furthermore, the LUAD-TCGA dataset showed a positive correlation between SLC7A5 and GAPDH mRNA expression in the cancer patient samples (r = 0.45, p = 1.55E−26)." (PMID 37095081, 2023). "Moreover, overexpression of the tryptophan-transport- and metabolism-related genes SLC1A5, SLC7A5, SLC7A8, and TDO2 in tumor cells also provides potential strategies for cancer therapy." (PMID 37545500, 2023). "Moreover, treatment with Dasatinib and PF573228 abrogated the transcriptional activation of SLC7A5/SLC3A2 and SSP enzymes induced by AA restriction and enhanced the inhibitory effect of low AA on cancer cell proliferation." (PMID 37880212, 2023). "With respect to the genes having interaction(s) with miRNAs, we realized four down-regulated vDEGs (TMEM100, MYH11, CHRDL1, and FAM107A) to the accompaniment of five up-regulated vDEGs (KLK10, CLDN1, SLC6A6, MMP11, and SLC7A5) being documented by the GEPIA in both COAD and READ cancer types." (PMID 35333898, 2022). "SLC7A5 (L-type amino acid transporter 1 or LAT1) forms heterodimer with SLC3A2 to function as a Na+ independent, large neutral amino acid antiporter that is commonly overexpressed in cancer cells." (PMID 35755805, 2022). "The interplay between SLC1A5 and SLC7A5, belonging to the SLC7 family of glutamine antiporters, was previously suggested, pointing towards the enhanced entry of essential amino acids via SLC7A5, activated by Gln flux through SLC1A5, as a strategy contributing to cancer progression." (PMID 35158820, 2022). "In addition, SLC1A5 (ASCT2), SLC7A5 (LAT1), SLC7A11 (xCT), and SLC6A14 (ATB0+) have been shown to be positively expressed in cancer." (PMID 33937189, 2021). "Furthermore, it has been demonstrated that SLC38A1/SNAT1 and SLC38A2/SNAT2 activity is essential to mediate net glutamine uptake and glutaminolysis in cancer cells, whereas SLC1A5/ASCT2 and SLC7A5/LAT1 coordinate intracellular amino acid pools." (PMID 34003553, 2021). "Our study demonstrated that in most cancer types, SLC1A5, SLC7A5, SLC7A11, and SLC3A2 were highly expressed and indicative of poorer survival outcomes, while the effects of changes in the expression of GLS2 and GLS depended on the type of cancer under consideration." (PMID 34573287, 2021). "The transcription factor MYC, one of the most frequently amplified genes in human malignancies, is a master-regulator of amino acid metabolism promoting the expression of transporter proteins such as SLC1A5, SLC7A5 and SLC43A1 and thus, driving cancer growth by effective amino acid delivery." (PMID 33401748, 2021). "A selective SLC7A5 inhibitor, JPH203, has been shown to suppress cancer cell growth." (PMID 33505538, 2021). "In addition, we found that silencing of both SLC7A5 and SLC3A2 by RNA interference impaired the proliferation of the ER+ cancer cells." (PMID 32093034, 2020).